LINC00636 (long independently transcribed non-coding RNA 636)
Gene: Long non-coding RNA gene on chromosome 3 (107,834,562 to 107,936,823, forward strand). Ensembl gene ENSG00000240423.
Diseases named in the same sentence as LINC00636 in open-access papers:
LINC00636 is named in the same sentence as 4 diseases in open-access papers, as found by Europe PMC text mining. Sharing a sentence is not in itself a finding about the gene and the disease. The quoted sentences say what the papers report.
atrial fibrillation (1 paper, 2021). A disorder characterized by an electrocardiographic finding of a supraventricular arrhythmia characterized by the replacement of consistent P waves by rapid oscillations or fibrillatory waves that vary in size, shape and timing and are accompanied by an irregular ventricular response. "Exosomes containing LINC00636 in human pericardial fluid promoted the expression of miR-450a-2-3p to inhibit MAPK1 and improve cardiac fibrosis in patients with atrial fibrillation." (PMID 34257520, 2021).
breast carcinoma (1 paper, 2026). "Together, our findings uncover a common insertion-deletion variant that fine-tunes the regulatory activity of a bifunctional super-enhancer, suggest a protective role for the insertion allele, and establish a previously unrecognized role for LINC00636 in senescence and breast cancer biology." (PMID 42183347, 2026). "Here, we identified a bifunctional super-enhancer that regulates the expression of cancer-promoting genes LINC00636 and CD47 in breast cancer." (PMID 42183347, 2026).
LINC00636 also shares sentences with these, for which no sentence is quoted: cancer (1 paper); tumor (1).